UGT1A4 (UDP glucuronosyltransferase family 1 member A4)
Description:
[Isoform 1]: UDP-glucuronosyltransferase (UGT) that catalyzes phase II biotransformation reactions in which lipophilic substrates are conjugated with glucuronic acid to increase the metabolite's water solubility, thereby facilitating excretion into either the urine or bile. Essential for the elimination and detoxification of drugs, xenobiotics and endogenous compounds. Involved in the glucuronidation of calcidiol, which is the major circulating form of vitamin D3 essential for the regulation of calcium and phosphate homeostasis. Also glucuronidates the biologically active form of vitamin D3, calcitriol, probably leading to its biliary transport and intestinal reabsorption. Involved in the glucuronidation of arachidonic acid (AA) and AA-derived eicosanoids including 15-HETE, 20-HETE and PGB1. Catalyzes N-glucuronidation of tobacco alkaloids, tobacco-specific nitrosamines and tricyclic antidepressants. [Isoform 2]: Lacks UDP-glucuronosyltransferase (UGT) activity but acts as a negative regulator of isoform 1.
Synonyms: hUG-BR2; UDPGT 1-4; UGT1-04; UGT1.4; UGT-1D; UGT1D; UGT1A4S
Tractability: Small molecule: a high-quality ligand is known. Antibody: UniProt predicts a signal peptide or a membrane-spanning region. PROTAC: its protein half-life has been measured; a small molecule that binds it is known.
Target class: Enzyme; Transferase
Safety:
Unwanted effects reported when the protein is acted on. In parentheses: how it was acted on, where the effect was seen, and who reports it.
adverse reactions (source: ClinPGx)
hand-foot syndrome (source: ClinPGx)
hyperbilirubinemia (source: ClinPGx)
hyperprolactinemia (source: ClinPGx)
liver failure (source: ClinPGx)
nephrolithiasis (source: ClinPGx)
neutropenia (source: ClinPGx)
Gene: Protein-coding gene on chromosome 2 (233,718,736 to 233,773,300, forward strand). Ensembl gene ENSG00000244474.
Subcellular location: Endoplasmic reticulum membrane
Pathways (Reactome):
Metabolism: Glucuronidation; Heme degradation
Disease: Defective UGT1A4 causes hyperbilirubinemia
Drug ADME: Aspirin ADME
Gene Ontology:
Molecular function: enzyme binding; glucuronosyltransferase activity; protein homodimerization activity; retinoic acid binding; enzyme inhibitor activity; protein heterodimerization activity; UDP-glycosyltransferase activity
Biological process: detoxification; vitamin D3 metabolic process; xenobiotic catabolic process; bilirubin conjugation; cellular response to glucocorticoid stimulus; estrogen metabolic process; flavone metabolic process; glucuronate metabolic process; heme catabolic process; liver development; monocarboxylic acid metabolic process; steroid metabolic process
Cellular component: endoplasmic reticulum; endoplasmic reticulum membrane
Genetic constraint (gnomAD): Loss-of-function variants: 32 observed, 41.83 expected, observed/expected ratio (o/e) 0.76, 90% interval 0.58 to 1.03. The upper end of that interval is the gene's LOEUF score, 1.03, which puts it in group 4 of 6, group 1 being the genes least tolerant of losing a copy. Missense variants: 748 observed, 705.38 expected, observed/expected ratio (o/e) 1.06, 90% interval 1 to 1.13. Synonymous variants: 283 observed, 277.23 expected, observed/expected ratio (o/e) 1.02, 90% interval 0.93 to 1.13.
Homologues: Orthologues: rabbit UGT1-6 (78% identical), mouse Ugt1a5 (75% identical), mouse Ugt1a2 (74% identical), zebrafish ugt2a7 (40% identical), zebrafish ugt2b5 (39% identical), zebrafish ugt2b1 (38% identical), zebrafish si:ch73-334d15.1 (37% identical), zebrafish ugt5a2 (35% identical), zebrafish ugt5c2 (35% identical), zebrafish ugt5a1 (35% identical), zebrafish ugt5b4 (35% identical), zebrafish ugt5c1 (35% identical), and 96 more. Paralogues in human: UGT1A5 (93% identical), UGT1A3 (93% identical), UGT1A1 (72% identical), UGT1A9 (68% identical), UGT1A8 (67% identical), UGT1A6 (67% identical), UGT1A10 (67% identical), UGT1A7 (67% identical), UGT2B4 (44% identical), UGT2B17 (43% identical), UGT2A3 (43% identical), UGT2B10 (43% identical), and 9 more.
Diseases named in the same sentence as UGT1A4 in open-access papers:
UGT1A4 is named in the same sentence as 22 diseases in open-access papers, as found by Europe PMC text mining. Sharing a sentence is not in itself a finding about the gene and the disease. The quoted sentences say what the papers report.
breast carcinoma (8 papers, 2012 to 2026). "Frequency of CYP3A4*1B, CYP3A5*3 and UGT1A4*2 SNPs in 126 Croatian breast cancer (BC) patients and possible association with anastrozole-induced undesirable side effects were analyzed." (PMID 32456253, 2020). "In addition, assessment of CYP3A4, CYP3A5 and UGT1A4 variant alleles and knowledge about their allelic frequency in the Croatian population may lead to personalized breast cancer therapy." (PMID 32456253, 2020). "Glucuronidation of fulvestrant and the aromatase inhibitor anastrozole occurs via the UDP-glucuronosyltransferase 1A4 (UGT1A4), which was upregulated by fulvestrant in breast cancer cells via MYB." (PMID 38835346, 2024). "UGT2B7 and UGT1A4 showed a similar down-regulated pattern in breast cancers compared to normal breast tissues." (PMID 30349745, 2012). "This is the case for UGT2B7 induced by several anti-cancer agents in liver cell models, for UGT2B15 induced by tamoxifen and UGT2B17 induced by exemestane in breast cancer-cell models, as well as for UGT1A4 induced by fulvestrant in breast cancer and liver cell models." (PMID 32047295, 2020). "Therefore, the objective of the present study was to investigate the association between certain ESR1, ESR2, HER2, UGT1A4, and UGT2B7 single nucleotide polymorphisms and breast cancer." (PMID 31888550, 2019). "Quantification of UGT mRNA in breast tissues revealed that UGT1A4, UGT1A10, and UGT2B7 mRNA levels were decreased in breast cancers as compared to normal breast tissues." (PMID 30349745, 2012). "Specifically, UGT1A1 and UGT1A4 were not expressed in 5 normal breast specimens and 40 and 39 breast cancers, respectively." (PMID 30349745, 2012).
epilepsy (4 papers, 2014 to 2024). A brain disorder characterized by episodes of abnormally increased neuronal discharge resulting in transient episodes of sensory or motor neurological dysfunction, or psychic dysfunction. "Analysis of the expression of UGT1A4 by immunohistochemistry in brain from patients with epilepsy indicated high expression in BBB endothelial cells and neurons with variable levels of UGT1A4 expression among the brain specimens analyzed." (PMID 25389387, 2014). "Allelic and genotype frequencies of the metabolism enzymes UGT1A4 and UGT2B7 in Chinese patients with epilepsy." (PMID 31404235, 2019).
Cirrhosis (2 papers, 2021 to 2025). A chronic disorder of the liver in which liver tissue becomes scarred and is partially replaced by regenerative nodules and fibrotic tissue resulting in loss of liver function. "And AOX1's expression was remarkably related to histological differentiation, satellite lesions, and vascular cancer embolus while UGT1A4's expression was remarkably related to histological differentiation, satellite lesions, pN, and cirrhosis." (PMID 34337056, 2021). "Since UGT enzymes contribute to the metabolism of asciminib, for severe HI, a ‘modified Sim-Cirrhosis CP-C’ population, accounting for the reduced activity of UGT2B7 and UGT1A4 in such patients, was also used." (PMID 41155903, 2025).
Allergy (1 paper, 2019). An allergy is an immune response or reaction to substances that are usually not harmful. "However, the UGT1A4 rs12468274 and rs2011425 SNPs were found to be associated with allergy and tumor size, respectively." (PMID 31888550, 2019). "Regarding UGT1A4, its rs12468274 (TT vs CT) and rs2011425 SNPs were correlated with allergy (P = 0.001) and tumor size (P = 0.002)." (PMID 31888550, 2019).
breast tumor (1 paper, 2012). "In the present study, we characterized the mRNA expression of UGT1A1, UGT1A4, UGT1A8, UGT1A10, and UGT2B7 in normal and breast tumor tissues from AA and EA women." (PMID 30349745, 2012).
colorectal cancer (1 paper, 2022). A primary or metastatic malignant neoplasm that affects the colon or rectum. "For example, irinotecan is commonly used for treating colorectal cancer (COAD), and its active metabolite, SN-38, is primarily glucuronidated by UGT1A1 with weak activity from all other UGT1As except UGT1A4." (PMID 36428799, 2022).
Gilbert syndrome (1 paper, 2012). An autosomal recessive inherited disorder characterized by unconjugated hyperbilirubinemia, resulting in harmless intermittent jaundice. "Thus, we suggest that this UGT1A4 intronic SNP can be used as a genotyping marker for the Gilbert Syndrome allele of UGT1A1*27." (PMID 22514612, 2012).
Hypertension (1 paper, 2019). The presence of chronic increased pressure in the systemic arterial system. "Among the superfamily of UGT enzymes, UGT1 is strongly engaged in the metabolism of drugs used to treat epilepsy (UGT1A4), schizophrenia (UGT1A3 and UGT1A4), hypertension (UGT1A1, UGT1A3, UGT1A7, and UGT1A9), and hypercholesterolemia (UGT1A1 and UGT1A3)." (PMID 30959953, 2019).
Jaundice (1 paper, 2024). Yellow pigmentation of the skin due to bilirubin, which in turn is the result of increased bilirubin concentration in the bloodstream. "The alternate allele of a common missense variant affecting the sequence of UGT1A4 reduces the susceptibility to jaundice five-fold, which replicated in separate cohorts of neonates of African American and European ancestries." (PMID 39214992, 2024). "The most striking result is the UGT1A4 missense variant with a fivefold effect on the risk of neonatal jaundice (rs6755571)—the protective effect was replicated in cohorts of Nordic, African American and European American ancestries." (PMID 39214992, 2024).
neonatal jaundice (1 paper, 2024). A pigmentation disease characterized by a high level of bilirubin in the blood, causing a yellowing of the skin and other tissues of a newborn infant. "We sought to investigate whether the protective effects of the missense variant at UGT1A4 on neonatal jaundice were robust to these risk factors." (PMID 39214992, 2024).
schizophrenia (1 paper, 2020). A major psychotic disorder characterized by abnormalities in the perception or expression of reality. "We suggest that the UGT1A4 rs2011425 polymorphism affects olanzapine tolerability because it is associated with the observed side effects of olanzapine in schizophrenia patients, namely sympathetic dysfunction." (PMID 32070304, 2020). "We suggest that the UGT1A4 rs2011425 G variant affects the tolerability of olanzapine and is less likely to be associated with olanzapine side effects, including sympathetic dysfunction in schizophrenia patients." (PMID 32070304, 2020). "In this research, we found a significantly decreased LF component of HRV in olanzapine-treated schizophrenia patients with non-G alleles of the UGT1A4 polymorphism rs2011425." (PMID 32070304, 2020). "Thus, clinicians should consider the potentially elevated risk of ANS dysfunction in schizophrenia patients with UGT1A4 rs2011425 non-G alleles before beginning treatment with olanzapine monotherapy." (PMID 32070304, 2020).
tumor (5 papers, 2012 to 2022). "While the metabolic activities of UGT1A4 was only significantly related to protein expression ratio in HBV-positive HCC tumor tissues (R2 = 0.614, P < 0.05)." (PMID 26010150, 2015). "Similarly, significant decreasing protein and mRNA levels of UGT1A4 were also observed in tumor subsequently." (PMID 26010150, 2015). "By utilizing certain specific substrates for UGTs, we initially demonstrated that catalytic activities of UGT1A, UGT1A1, UGT1A4, UGT1A9 and UGT2B7 were significantly decreased in the tumor tissues in HBV-positive HCC patients." (PMID 26010150, 2015). "The results revealed that in the tumor human liver microsomes (HLMs), either Vmax (maximum reaction rate, Rmax for UGT1A1) or the clearance rates (Vmax/Km, Clint) of UGT1A, UGT1A1, UGT1A4, UGT1A9 and UGT2B7 were significant lower than those of in the adjacent normal HLMs." (PMID 26010150, 2015). "Given the increasing incidence and mortality of HCC with the high HBV-infection background in China, we systematically analyzed the metabolic function, protein and gene expression levels of UGT1A, UGT1A1, UGT1A9, UGT1A4 and UGT2B7 in HBV-positive HCC tumor and the adjacent normal tissues." (PMID 26010150, 2015). "Moreover, the tight correlation was found between the metabolic activity ratio and protein reduction ratio (R2 = 0.996, P < 0.001), and between the UGT1A4 metabolic activities of individual HLMs and the relative protein expression level in HBV-positive HCC tumor tissues (R2 = 0.828, P < 0.001)." (PMID 26010150, 2015).
cancer (3 papers, 2020 to 2023). A tumor composed of atypical neoplastic, often pleomorphic cells that invade other tissues. "In addition, innovative UGT1A4 inhibitors that specifically improved cancer cell susceptibility to chemotherapeutic drugs revealed a new possible method for combating cancer MDR." (PMID 37062547, 2023). "Furthermore, novel UGT1A4 inhibitors that selectively increased sensitivity of cancer cells to chemotherapeutic agents demonstrated a new potential strategy in overcoming cancer MDR." (PMID 32370233, 2020).
UGT1A4 also shares sentences with these, for which no sentence is quoted: cholelithiasis (1 paper); epileptic seizures (1); Hyperglycemia (1); hyperlipidemia (1); infection (1); influenza (1); liver dysfunction (1); panic attacks (1); vascular cancer (1).